MIR650 (microRNA 650)
Synonyms: hsa-mir-650; MIRN650
Gene: MicroRNA gene on chromosome 22 (22,822,776 to 22,822,871, forward strand). Ensembl gene ENSG00000284049.
Gene Ontology:
Biological process: miRNA-mediated post-transcriptional gene silencing
Homologues: Orthologues: chimpanzee ptr-mir-650 (98% identical).